ARID1A (AT-rich interaction domain 1A)
Diseases named in the same sentence as ARID1A in open-access papers (continued):
Sharing a sentence is not in itself a finding about the gene and the disease.
cancer (continued). "Importantly, this selective sensitivity was observed in multiple ARID1A-deficient cancers, irrespective of the cellular context." (PMID 36980292, 2023). "Further mechanistic investigations demonstrate that this vulnerability in cancer cells lacking ARID1D results from low basal levels of GSH due to reduced expression of SLC7A11 caused by impaired ARID1A-mediated chromatin remodeling and transcriptional activation." (PMID 36980292, 2023). "We also tested whether essentiality changes upon ARID1A dose reduction mimic those in cancer cell lines upon damaging mutations to the ARID1A gene, but found no strong signal." (PMID 37028423, 2023). "In addition, ARID1A can modulate gene transcription in cells, either directly controlling the expression of cancer related genes or indirectly by regulating the recruitment or activity of histone modifier enzymes, which add or remove histone modifications at gene regulatory regions." (PMID 36890819, 2023). "Also, the median number of VUS was higher in ARID1A+ cancers (12 vs. 9, P = 0.002)." (PMID 37711591, 2023). "Besides, the decreased ARID1A expression correlates with the poor outcome of cancers." (PMID 38017409, 2023). "One approach utilising synthetic‐lethal approaches for targeting ARID1A‐deficient cancers with the ATR inhibitor ceralasertib with or without the PARP (poly ADP ribose polymerase) inhibitor olaparib is being assessed in the ATARI phase II international proof‐of‐concept clinical trial." (PMID 35647895, 2022). "Likewise, the dual roles of ARID1A have also been revealed in cancer." (PMID 35967587, 2022). "Recent cancer genome sequencing studies revealed mutations in many epigenetic modifiers that are associated with various cancers, such as DNMT3A in acute myeloid leukemia, IDH1/2 in glioblastoma, CREBBP/EP300 in small-cell lung cancer and ARID1A in gastric cancer." (PMID 35973998, 2022). "The pausing defect could be rescued by upregulation of ARID1B, suggesting that both ARID1A and ARID1B control transcription via RNApol2 pausing and that dysregulated pausing likely mediates effects of ARID1A loss in cancers and possibly also neurodevelopmental disorders." (PMID 35615272, 2022). "Finally, USP11 can also control the stability of ARID1A by competing with TRIM32 to determine whether it is cancer-promoting or cancer-suppressing." (PMID 35359344, 2022). "For example, the BAF chromatin-remodeling complexes, which include BRG1 (SMARCA4) and BAF250a (ARID1A) that regulate transcription through the control of chromatin structure and the placement of polycomb repressive complex 2 (PRC2) across the genome are mutated in different cancer types." (PMID 35327559, 2022). "Recently, we have observed that that ARID1A-deficient cancer cells challenged with temozolomide and PARP inhibitor exhibited significant replication stress, replication fork instability, and DNA damage due to impaired BER arising from the ARID1A deficiency, leading to cell death." (PMID 36123603, 2022). "Hence, we studied ARID1A alterations in a large dataset of patients with cancer." (PMID 36077815, 2022). "In addition, favorable survival outcomes in ARID1A mutant patients when receiving ICB treatment were also revealed in a pan-cancer study, but merely 10 EC samples with the ARID1A mutation were included, not sufficient to demonstrate the survival difference." (PMID 36281289, 2022). "Cancer genome sequencing efforts reveal that in addition to mutations in growth-promoting signaling pathways such as in EGFR and KRAS, chromatin-modifying enzymes and epigenetic regulators such as KMT2D, ARID1A, and TET2 are also frequent targets of genetic alterations." (PMID 34236315, 2021).
cancer (continued). "It suggested that the inhibition of GLS1 or CCNE1 could significantly suppress the proliferation of ARID1A-mutated cancer cells in vitro and in vivo, respectively, but not in the wild type cells." (PMID 34715776, 2021). "ARID1A aberrations may lead to differential chromatin accessibility and therefore to blunted anti-cancer directed immune responses, e.g. by reduction of overall IFN-gamma production, diminished immune cell infiltration and insufficient long- term immune memory responses." (PMID 34335558, 2021). "In the TCGA study on muscle-invasive UC, about 90% of the cancers carried one or more mutations in KDM6A (encoding histone demethylase UTX), KMT2C, KMT2D (encoding histone methyltransferases MLL2 and MLL3), CREBBP, EP300 (histone acetyltransferases), and ARID1A (a SWI/SNF component)." (PMID 34885146, 2021). "Therefore, it is possible that cancer cells deficient in ARID1A or other SWI/SNF subunits share properties that are absent from noncancerous cells, and that some of those properties create vulnerabilities." (PMID 33917230, 2021). "Thus, deleterious ARID1A mutations are a common feature of OCCC and other cancers." (PMID 33917230, 2021). "Furthermore, one study showed that recurrently mutated cancer driver genes, such as KRAS, PIK3CA, PPP2R1A, and ARID1A, are also present in endometriosis without cancer association." (PMID 34202354, 2021). "Thus, ARID1A has a context-dependent oncogenic role in cancer." (PMID 34671561, 2021). "The reason for this could be that cancer cells lacking ARID1A and ARID1B expression are deficient in DNA repair and potentially vulnerable to DNA damage." (PMID 33467469, 2021). "However, growing evidence indicated that ARID1A may have a widespread suppressive role in various cancer entities." (PMID 33578810, 2021). "Here, by investigating a panel of cancer-associated genes in a Danish population, our data showed that patients were further stratified into four different molecular subgroups: “PIK3CA”, “ARID1A”, “PIK3CA-ARID1A” and “Undetermined”, in regard to the presence of mutation on these genes." (PMID 34680390, 2021). "These authors speculated that one possible explanation for lack of correlation is that loss of ARID1A expression is an early event in the development of cancer." (PMID 32334542, 2020). "ARID1A, a subunit of SWI/SNF complexes that controls how much “read access” the cellular transcription machinery has to DNA sequences, can have profound consequences on gene expression, and genes encoding chromatin-remodeling proteins are some of the most frequently mutated genes in human cancer." (PMID 32878261, 2020). "Based on the research above, we reasonably deduced that ARID1A or ARID1B mutation serves as a novel biomarker for ICIs treatment and could have a connection with factors that are proven to be associated with sensitivity to cancer immunotherapy." (PMID 32791957, 2020). "Thus, the cell line can be used for developing methods for early diagnosis, for investigating new targeting therapy including ARID1A and FGFR3, and for examining the involvement of ARID1A and FGFR3 mutation in the development, survival, and progression of cancer." (PMID 33143664, 2020).
cancer (continued). "Also, it has recently been shown that ARID1A mutations can render cancer cells sensitive to glutathione and glutamate-cysteine ligase synthetase catalytic subunit (GCLC) inhibitors, while they also increase the sensitivity of cancer cells to PI3K inhibitors." (PMID 32520976, 2020). "However, as depletion of ARID1A protein expression was found to significantly increase the sensitivity of cancer cells towards PI3K and AKT inhibitors, the expression of ARID1A could serve as a biomarker to predict the response for the inhibitors." (PMID 31481116, 2019). "In addition, ARID1A has been shown to foster resistance to cancer therapy." (PMID 31847141, 2019). "Thus, our study provides mechanistic understanding of the long-standing paradox between ARID1A’s role in maintaining mitotic integrity and the lack of genomic instability in ARID1A-mutated cancers." (PMID 31492885, 2019). "Moreover, the correlation between the loss of ARID1A immunoreactivity and reduced ARID1B levels indicates that ARID1B could be an attractive target for anti-cancer therapy." (PMID 29890703, 2018). "Another study demonstrated that the chromatin-remodeling factor ARID1B, forming the BAF complex together with ARID1A, represses the Wnt/ß-Catenin signaling pathway indicating this might contribute to cancer through deregulation of developmental and oncogenic pathways." (PMID 29451900, 2018). "Moreover, these genes had relatively high mutation rates in the pan-cancer data (KMT2D, 14.41%; ARID1A, 9.04%; NAV3, 8.52%), which might be overestimated due to the erroneous batch-biased variant calls, although this remains to be validated." (PMID 28399795, 2017). "However, therapeutic strategies targeting ARID1A-mutant cancer cells remain limited." (PMID 27486766, 2016). "As SWI/SNF subunits other than ARID1A are also frequently inactivated in cancer, cancer cells with SWI/SNF mutations may be more sensitive to oxidative stress and ROS-inducing agents may be used to target these cancers." (PMID 27486766, 2016). "Therefore, in the future the ability to adjust for the mutations of other genes could be fundamental for a better interpretation of the role of ARID1A and cancer outcomes." (PMID 26384299, 2015). "SWI/SNF mutations occur at a high frequency in TC, primarily involving the inactivation of SWI/SNF subunits ARID1A, ARID1B, ARID2, and PMRM1, which were found in several aggressive cancer types, including ATC." (PMID 40203790, 2025). "The aberrations of SMARCB1, SMARCA4, ARID1A, PBRM1, and SS18 within the SWI/SNF complex are frequently found in rare cancers and refractory cancers." (PMID 39625239, 2025). "Increasing evidence suggests that ARID1A directly regulates EMT and cell differentiation across several tissues and cancer types." (PMID 40429787, 2025). "The findings implied that patients harboring ARID1AMut exhibited longer survival rates following ICI therapy, providing further evidence of the central role of ARID1A in shaping the TME and the prognosis of cancer patients." (PMID 40406134, 2025). "Other known recurrent cancer genes with ≥10 occurrences include PLEC, PDGFRA, NF1, ARID1A, BCOR, and ACVR1." (PMID 41312385, 2025). "Chromatin remodeling factors like ARID2 and ARID1A, essential components of the SWI/SNF complex, are critical in regulating cancer progression and metastasis." (PMID 40872531, 2025). "Furthermore, we speculate that the broad functional connectivity of ARID1A may also relate to its driver role in cancer: network components with a high number of genetic interactions have been described as “buffers” or “capacitors” if their activity controls the exposure of knockout phenotypes." (PMID 40239999, 2025).
cancer (continued). "Deletions of ARID1A and ARID1B drive hyperproliferation and dedifferentiation in several human cancers." (PMID 40362680, 2025). "ARID1A was highly expressed in cancer cell and fibroblasts, POU2F2 was significantly expressed in cancer cell, and SPI1 was highly specific to myeloid cell, suggesting its involvement in immune regulation." (PMID 40396172, 2025). "All these variants are present in heterozygosity, and many of them occurred in tumor suppressor genes and transcription factors that have a role in cancer development and T cell function, like MSH6, ARID1A, CARD11, CBL and SRC30–33." (PMID 38688902, 2024). "LOF of the components of the SWI/SNF complex, mainly ARID1A, SMARCA4, or SMARCB1, has been demonstrated to sensitize cancer cells to PRC2 inhibitors." (PMID 39500892, 2024). "A wide variety of benign and malignant tumors with alterations in several genes belonging to the SWI/SNF complex have been described, including SMARCB1, SMARCA4, SMARCA2, and ARID1A." (PMID 39590317, 2024). "Previously reported focal CNAs in MSS primary cancers included single-copy and double-copy gains involving CCND1, ERBB2, MYC and KLF5, and deletions of ARID1A, SMAD4 and APC7,31." (PMID 39112709, 2024). "Specifically, the ARID1A subunit has been identified as a direct regulator of glutaminase 1 (GLS1), a gene pivotal in cancer metabolism." (PMID 38374872, 2024). "While ARID1A mutations are known to contribute to cancer through the disruption of the SWI/SNF chromatin remodeling complex, the novel variants identified in this study suggest that there may be additional, uncharacterized mechanisms by which ARID1A loss contributes to tumorigenesis." (PMID 39296440, 2024). "Specifically, ARID1A interacts with EZH2 and antagonized EZH2-mediated IFN responsiveness in cancer cells." (PMID 38461299, 2024). "Identifying a number of putative drivers, ARID1A, CHD4, HCFC1, STAG2, SMARCA4, and NCOR1 are known cancer driver genes." (PMID 37444571, 2023). "SMARCA4-deleted cancer cells are highly dependent on the paralog SMARCA2 for their survival, and ARID1B is required for the survival of ARID1A-depleted cells as well." (PMID 37371564, 2023). "In addition to cancer cells, multiple cell types in the TME, including immune cells may be differentially influenced by the metabolic rewiring and epigenetic alterations caused by the driver mutation, such as ARID1A deficiency." (PMID 36980292, 2023). "ARID1A alterations compromise the MMR pathway and increase the number of TILs and PD-L1 expression in some cancers." (PMID 36793735, 2023). "EZH2 inhibition led to impaired proliferation of several human cancer cell lines with mutant SWI/SNF genes including BRG1 (SMARCA4), PBRM, and ARID1A." (PMID 38275587, 2023). "CNV analysis indicated that heterozygous deletion of ARID1A was prevalent in ESCA and KICH; BRCA2 CNV deletion was more common in Pan-cancer than BRCA1 CNV deletion." (PMID 37264024, 2023). "The prognostic genes for ACC and LIHC had a shared enrichment for SWI/SNF chromatin remodeler genes with SMARCD1 in ACC, and ARID1A and CHAF1B in LIHC, being the most significantly prognostic SWI/SNF genes (P < 0.0001) in these two cancer types." (PMID 37973839, 2023). "In summary, ARID1A, as a component of the SWI/SNF complex, plays a context-dependent tumor suppressive and oncogenic role in cancer." (PMID 36844227, 2023). "ARID1A (BAF250a), though connected with a superior outcome of ICB treatment in several cancer types, has rarely been reported for its prognostic and predictive ability in the immunotherapy cohort of EC." (PMID 36281289, 2022).
cancer (continued). "The mutational rates and variation types of six SWI/SNF complex genes (ARID1A, ARID1B, ARID2, SMARCA4, SMARCB1, and PBRM1) were analyzed retrospectively by integrating next-generation sequencing data of 4591 cases covering 18 cancer types." (PMID 36371186, 2022). "The evidence above indicates the mechanisms related to ARID1A-KD through which a better response to ICIs occurs, and further verification was performed using EGFR-mutant LUAD cohorts from our cancer center and TCGA." (PMID 36229854, 2022). "Genetic alterations in ARID1A (12%), ARID1B (5%), ARID2 (6%) and ARID5B (2.6%) were identified in multiple cancer types." (PMID 35239432, 2022). "ARID1A, which directly interacts with chromatin as a core subunit of the SWI/SNF complex, plays critical roles in cancer cell development, differentiation, and proliferation." (PMID 35198440, 2022). "ARID1A and SMAD4, which annotated deletions in the TCGA STAD cohort, were inferred to be deleted in the cancer cell cluster." (PMID 35087207, 2022). "Seven top upregulated emRNAs and related to ccRCC or/and multiple malignant tumors, including CUL9, ATM, ARID1A, KMT2D, PBRM1, PREX2, and SETD2, were selected as candidate biomarkers for further testing." (PMID 36002886, 2022). "The expression levels of ARID1A and JARID1C were relatively high, but there was striking heterogeneity across the different cancer types for specific family members." (PMID 35127746, 2021). "Similar to ARID1A, the regulation of BRG1 in tumorigenesis of different cancers is rather complicated, which is considered to be tissue type and cellular context dependent." (PMID 34671561, 2021). "Besides, ARID1A alterations or expression loss could lead to the resistance to EGFR-TKIs via a variety of processes during the tumorigenesis and development of cancers, including epithelial to mesenchymal transition, angiogenesis and the inhibition of apoptosis." (PMID 34715776, 2021). "Moreover, we performed Reactome analysis on DEGs, the results showed that, as Arid1a depletion, an extensive effect exerted on biological processes involving the previously reported pathways including packing of telomere ends and a series of cancer-related processes." (PMID 34689165, 2021). "ARID1A is a core DNA-binding subunit of the BAF chromatin remodeling complex, and is lost in up to 7% of all cancers." (PMID 33826602, 2021). "Preclinical studies indicate that ARID1A mutant cancers display sensitivity to ATR inhibition while tumors without ARID1A mutations may be sensitive to Ataxia telangiectasia and Rad3 related (ATR) inhibitors in combination with poly-ADP ribose polymerase (PARP) inhibitors." (PMID 34518240, 2021). "However, significantly improved PFS or prolonged stable disease was achieved in certain groups of patients, such as patients with ARID1A-deficient OCCC or PTPRB-mutated STS, suggesting that ENMD-2076 may have clinical benefit in these molecular subtypes of cancer." (PMID 34050264, 2021).